TEX29 (testis expressed 29)
Synonyms: C13orf16; bA474D23.1; MGC35169
Tractability: Antibody: UniProt predicts a signal peptide or a membrane-spanning region.
Gene: Protein-coding gene on chromosome 13 (111,316,184 to 111,344,249, forward strand). Ensembl gene ENSG00000153495.
Subcellular location: Membrane
Gene Ontology:
Molecular function: protein binding
Cellular component: membrane
Genetic constraint (gnomAD): Loss-of-function variants: 21 observed, 16.19 expected, observed/expected ratio (o/e) 1.3, 90% interval 0.92 to 1.8. The upper end of that interval is the gene's LOEUF score, 1.8, which puts it in group 6 of 6, group 1 being the genes least tolerant of losing a copy. Missense variants: 161 observed, 184.56 expected, observed/expected ratio (o/e) 0.87, 90% interval 0.77 to 0.99. Synonymous variants: 78 observed, 75.71 expected, observed/expected ratio (o/e) 1.03, 90% interval 0.86 to 1.24.
Homologues: Orthologues: chimpanzee TEX29 (97% identical), dog TEX29 (60% identical), pig TEX29 (56% identical), macaque TEX29 (53% identical), rat Tex29 (44% identical), mouse Tex29 (42% identical).
Diseases named in the same sentence as TEX29 in open-access papers:
TEX29 is named in the same sentence as 1 disease in open-access papers, as found by Europe PMC text mining. Sharing a sentence is not in itself a finding about the gene and the disease. The quoted sentences say what the papers report.
age-related macular degeneration (1 paper, 2025). Age-related loss of vision in the central portion of the retina (macula), secondary to retinal degeneration. "In mCNV, a recent meta-GWAS uncovered a new locus (near TEX29/LINC02337) as a shared genetic susceptibility with age-related macular degeneration (AMD), along with other risk variants at CETP and the ARMS2 regions." (PMID 40909333, 2025).